IL4 (interleukin 4)
Diseases named in the same sentence as IL4 in open-access papers (continued):
Sharing a sentence is not in itself a finding about the gene and the disease.
diabetes (continued). "Transgenic NOD mice expressing IL-4 in the pancreatic islets are protected from the development of diabetes." (PMID 20686610, 2010). "It had previously been suggested that the reason Idd9 congenic mice are protected against diabetes, despite having an extensive islet infiltrate, could be due to the priming of a non-pathogenic anti-islet T cell response that releases the protective cytokine IL4." (PMID 17254331, 2007). "Although IL-4 deficiency alone does not exacerbate insulitis severity in NOD mice, experimental strategies that enhance IL-4 expression, including systemic or local administration, or genetic engineering of β-cells and dendritic cells, can delay diabetes onset and reduce disease incidence." (PMID 40804870, 2025). "Dendritic cell-derived IL-1 has a stimulatory effect on T cell function in diabetes and the reduced IL-4 signaling from DETCs may induce a net Th1 bias." (PMID 38502310, 2024). "Moreover, except for its osteogenic properties, ART can also alleviate the incidence of diabetes through increasing the proportion of IL-4-producing CD4+T lymphocytes (Th2) while reducing IFN-γ-producing T lymphocytes (Th1)." (PMID 38509482, 2024). "Subgroup A1 was characterized by significantly higher levels of IL-35 and IL-10 than the other subgroups of patients with diabetes, and statistically higher IL-4 when compared to subgroup B. Our study shows that the effect of metabolic memory fades away with the increasing duration of diabetes." (PMID 38542165, 2024). "Similarly, the gelatin/β-tricalcium phosphate scaffold with sustained release of IL-4 to induce M2 polarization enhanced tooth extraction socket healing in diabetes." (PMID 39258053, 2024). "In the periodontally healthy sites, the concentrations of IL-4, IL-5, IL-7, and IL-13 were decreased in the diabetes group compared to those in the control group; TGF-β concentrations were also decreased in the control group versus those in the rest of the groups (p < 0.05)." (PMID 37835794, 2023). "On the other hand, a decreased secretion of anti-inflammatory cytokines such as transforming growth factor-beta (TGF-β), interleukin-4 (IL-4), and interleukin-10 (IL-10) may also lead to the aggravation of periodontal inflammation in diabetes patients." (PMID 37664859, 2023). "Besides, the M1 polarization markers, including IL-1β, IL-6 and TNF-α increased in the isolated retinal microglia from diabetes rats, with the decreasing M2 polarization markers such as IL-4, IL-10 and TGF-β." (PMID 35300330, 2022). "Moreover, wound administration of mouse Mφs activated IL-4 or IL-10 in vitro into the M2-like phenotype damaged skin wound healing in a diabetic mouse model." (PMID 36582221, 2022). "Lower IL-4 levels were also found when PD patients had smoking habits and/or diabetes." (PMID 31978095, 2020). "The protective effect of IL4 has been shown in murine models of rheumatoid arthritis and diabetes." (PMID 33664727, 2020). "In addition, IL-4 and IL-1RN (VNTR) gene polymorphisms have together been linked to frailty syndrome and type 2 diabetes mellitus." (PMID 31650822, 2019). "Interestingly, IL-4 transduced tolDCs were reported by several studies to prevent diabetes in NOD mice, including at later pre-onset age or even restore normoglycaemia in diabetic animals." (PMID 31139178, 2019). "IL-4 could inhibit IL-2-induced activation of NK and show anti-inflammatory roles based on its protective effects in diabetes." (PMID 30881587, 2019). "It is therefore tempting to hypothesize that tolerogenic DCs function in diabetes-resistant mice express high levels of active C/EBPβ as we observed in the case of tolerogenic GM/DCs as compared to IL-4/DCs." (PMID 30544623, 2018). "hASC and hASC-CM treatments were able to normalize cytokine levels, as demonstrated by the IFN-γ and IL-2 decrease (p < 0.001 vs STZ) and IL-10 and IL-4 increase when treatments were performed 6 weeks after diabetes induction and cytokines measured 8 weeks later." (PMID 28851944, 2017).
diabetes (continued). "On the other hand, enhanced IFN-γ production increased susceptibility to MLD-STZ-induced type 1 DM; while downregulation of Th2 cells (and so decrease in the production of IL-4 and IL-10) downregulated the disease; and inhibition of IL-1 activity downregulated diabetes induction." (PMID 28824543, 2017). "There are no studies in the literature investigating the expression of proinflammatory(IFN-γ, TNF-α, IL-17A) and anti-inflammatory (IL-4, IL-10) cytokines in serum ofpatients with type 2 diabetes mellitus submitted to duodenojejunal bypass surgery withileal interposition without gastric resection." (PMID 26734798, 2015). "However, protection from diabetes in NOD mice is still maintained if iNKT cells are unable to produce or induce IL-4 and other regulatory cytokines." (PMID 22046304, 2011). "Furthermore, a shift towards an anti-inflammatory state is indicated by the increases in IL-4 and IL-10 levels, which could help manage diabetes by reducing chronic inflammation and creating a favourable immunological environment." (PMID 40299229, 2025). "Additionally, the increases in IL-4 and IL-10 levels point to a shift towards an anti-inflammatory state, promoting a favourable immunological environment that could benefit diabetes management by mitigating chronic inflammation." (PMID 40299229, 2025). "However, in diabetes, the expression of IL-4 is significantly reduced, which may hinder M2 polarization and prolong chronic inflammation, ultimately exacerbating liver fibrosis." (PMID 40362271, 2025). "Also, treatment of NOD mice with recombinant IL4 resulted in protection from diabetes." (PMID 37090926, 2023). "In addition, a recent study has also reported that chronic inflammation as observable by altered levels of anti-inflammatory cytokine levels including IL-4 and IL-10 may play a predictive role in disorders such as type 2 diabetes mellitus development." (PMID 31991875, 2020). "Further previous studies confirm that MHC Class I and II deficient DC transduced to express soluble IL-4 do not delay diabetes onset, confirming that there is indeed a critical role for antigen presentation by the transduced DC for therapeutic effects to be seen." (PMID 20686610, 2010). "Beyond IL-4 and IL-10, other members of the TGF superfamily, such as TGF-β3, BMP-2, and BMP-4, are involved in regulating macrophages for bone regeneration in diabetes as well, making them potential targets in future research on biomaterial-based therapy." (PMID 39258053, 2024). "IL‐4 and IL‐17, along with high‐density lipoprotein cholesterol (HDL‐C), sex, smoking, and diabetes, independently predicted CAD." (PMID 38146141, 2023). "Treatment with quercetin largely inhibited SARS-CoV-2 N protein-induced F4/80+ macrophages infiltrating the diabetic kidney and greatly suppressed the mRNA expression of IL-6, TNF-α, and MCP-1 while increasing the expression of IL-4 and IL-10 mRNA levels." (PMID 38022581, 2023). "Surprisingly, in IL-4 knockout NOD mice, where Th2 response is blocked, H. polygyrus infection still conferred protection from diabetes." (PMID 36059452, 2022). "Compared with previous studies, we evaluated immunologic indices, including IL-6, TNF-α, IL-4, IL-10, TGF-β1 levels, and regulatory T cells, in addition to general diabetes evaluation." (PMID 35725652, 2022). "Previous studies showed that both administration of recombinant IL-4 and pancreatic expression of IL-4 were able to protect NOD mice from diabetes." (PMID 33604389, 2021). "Diabetes related biomarkers: GIP, GLP-1, leptin, glucagon and inflammatory cytokines: IL-4, IL-5, IL-10, IL-12, IFN-g and TNF-α were significantly affected by HFB diet compared to HF diet." (PMID 34441468, 2021). "Combined administration of L. lactis MG1363 FnBPA+ (pValac::dts::IL-4) and L. lactis MG1363 FnBPA+ (pValac::IL-10) resulted in protection against diabetes in NOD mice." (PMID 33604389, 2021).
diabetes (continued). "Diabetes related biomarkers, gastric inhibitory polypeptide (GIP), leptin, glucagon, and inflammatory cytokines interleukin 4 (IL-4) and IL-5, 10 and 12, IFN-g and TNF-α were significantly affected by HFB diet." (PMID 34441468, 2021). "Diabetes-induced p38 MAPK activation promotes the production of inflammatory factors, including TNF-α, IL-1, IL-4, IL-6 and IL-8, by tissues and cells." (PMID 27413117, 2016). "To determine how the enhanced suppressive effect on diabetes was mediated by Th2 cells in CTB-Ins-GAD-treated mice, we investigated the frequency of IFN-γ-secreting T cells (Th1) and IL-4-secreting T cells (Th2) using ELISPOT assays." (PMID 26783749, 2016). "Additional models controlling for gender, pulmonary source of infection, and diabetes were built for EGF, VEGF, IL4, IL5, and IL13." (PMID 26064774, 2015). "DNA vaccination with insulin B-chain prevented diabetes onset in NOD and RIP-NP mice through a mechanism involving IL-4 production, and administration of a DNA vaccine encoding proinsulin was effective in both prevention and reversal of diabetes in NOD mice." (PMID 23405091, 2013). "Transgenic expression of IL-4 in β cells under the control of the insulin promoter in NOD mice suppresses insulitis and diabetes; however, islet expression of IL-4 is incapable of preventing islet rejection in diabetic recipients." (PMID 22690214, 2012). "Correlation analysis showed that IL-2, IL-4, IL-7, EOTAXIN, and IFN-γ concentrations in tears were negatively correlated with duration of diabetes, i.e., the shorter the duration of diabetes the higher the cytokine concentration." (PMID 21203348, 2010). "The roles of certain cytokines and molecules, such as IL-4, TNF-γ, and TIMP-2, in driving the progression of periodontal disease and alveolar bone loss in individuals with diabetes, have not been completely clarified." (PMID 40075856, 2025). "The adoptive transfer of dendritic cells (DC) genetically modified to express interleukin-4 (IL-4) significantly reduces the onset of diabetes in both normoglycemic and prediabetic nonobese diabetic (NOD) mice." (PMID 40299229, 2025). "Among subjects with diabetes, those with TIR ≤ 70% had higher levels of IL-1α, IL-1β, IL-6, IL-12 p70, IL-16, LIF, M-CSF, MCP-1, MCP-3, RANTES, TNF-α, TNF-β, and b-NGF, and lower levels of IL-1α, IL-4, IL-10, GM-CSF, and MIF than individuals with TIR > 70%." (PMID 37893217, 2023). "It was reported that children with one or two diabetes-related antibodies (IA-2 and/or GAD65) have significantly higher levels of IL-1β and IL-2 and lower levels of IL-4 than children with diabetes who were negative for these markers." (PMID 37893217, 2023). "We also observed that anti-inflammatory markers (as in the case of IL-10 and IL-4) were more expressed in the circulating leukocytes of obese individuals with or without diabetes when compared to lean individuals." (PMID 35069589, 2021). "GM-CSF tolDCs were inferior to GM-CSF+IL-4 generated ones in diabetes prevention in NOD mice, especially when cultured without antigen." (PMID 31139178, 2019). "Nevertheless, it is known that exogenous administration of IL-13 or IL-4 reduces the incidence and delays the onset of diabetes in the NOD mouse model of type 1 diabetes and that IL-4 and IL-13 each exert direct pro-survival effects in human pancreatic islet cells." (PMID 30338340, 2019). "Expression of IL-4 prevented the onset of insulin-dependent diabetes mellitus in nonobese diabetic mice." (PMID 30345315, 2018). "It has been shown that bone marrow-derived tolerogenic DCs (tolDCs) generated in the presence of GM-CSF and IL-4 in an antigen-nonspecific manner displayed diabetes-preventive properties." (PMID 29503651, 2018). "Previous research has reported a preventive effect of IL4 on the onset of diabetes in non-obese diabetic mice (NOD mice)." (PMID 28258520, 2017).
diabetes (continued). "When cytokine levels were measured 14 weeks after diabetes induction, a clear shift toward a Th1 pattern was present, characterized by higher IFN-γ and IL-2 secretion (respectively, p < 0.001) and lower IL-4 (p < 0.05) and IL-10 levels (p < 0.01)." (PMID 28851944, 2017). "Furthermore, both interleukin (IL)-4 and human GAD65 plant tissue were required to protect NOD mice from diabetes." (PMID 26783749, 2016). "It is also striking that diabetes protection by TLR3 stimulation required the presence of IL-4 which was not the case for TLR4-induced protection." (PMID 20628601, 2010). "Following adjustment for age, sex, triglyceride levels, diabetes, and hypertension, a covariate variance analysis revealed significant differences between these groups with respect to plasma levels of TWEAK, TNF-α, IL-10, and IL-4 (PTWEAK = .017, PTNF-α < .001, PIL-10 = .010, PIL-4 = .016)." (PMID 40629651, 2025). "After adjusting for hypertension, diabetes, triglyceride levels, gender, and age, Student t tests covariance confirmed significant differences in the enrichment levels of TWEAK, TNF-α, IL-10, and IL-4 of patients in case group (PTWEAK = .017, PTNF-α < .001, PIL-10 = .010, PIL-4 = .016)." (PMID 40629651, 2025). "Therefore, the aim of this study was to investigate the effect of orally administered Lactococcus lactis MG1363 FnBPA+ strains carrying plasmids encoding IL-4 and IL-10 in the streptozotocin- (STZ-) induced diabetes model and in nonobese diabetic (NOD) mice." (PMID 33604389, 2021). "Although these animals will eventually develop diabetes which is corrected with IL-4 injection, the hypoglycemia in the IUGR animals does not appear until adulthood, and thus, the effects on myelination in this model were direct and not due to rescue of the metabolic syndrome." (PMID 31839002, 2019). "Seventeen patients with type 2 diabetes mellitus under clinical management weresubmitted to surgery and blood samples were collected before and six months aftersurgery for evaluation of the serum profile of proinflammatory (IFN-γ, TNF-α,IL-17A) and anti-inflammatory cytokines (IL-4, IL-10)." (PMID 26734798, 2015). "The increased production of the IL-4 and the anti-inflammatory Th2-cytokine IL-10 in DENV-infected mononuclear cells of the diabetes in our study might result from a counterbalance to the comparatively highly produced pro-inflammatory cytokines/chemokines in the diabetic hosts." (PMID 24078930, 2013). "Furthermore, we and others have demonstrated that adoptive transfer of dendritic cell (DC) transduced ex vivo with IL-4-expressing adenoviral and retroviral vectors traffic to the spleen and pancreatic lymph node of NOD mice and are capable of preventing diabetes onset." (PMID 20686610, 2010). "However, Idd9.IL4KO mice developed the same low frequency of diabetes (3 %, n = 29) as Idd9 congenic mice (3 %, n = 33), demonstrating that IL4 expression is not required for diabetes protection in the Idd9 congenic strain." (PMID 17254331, 2007). "Our results indicate that susceptibility to NODAT might be monitored by genotyping KTRs who developed diabetes compared with KTRs who did not develop diabetes for selected major Th 1(IFNG)/ Th-2 (IL-4)/TGFB, T-reg in addition to IL-6, macrophage derived cytokines." (PMID 33727573, 2021). "Diabetes increased IL-10, IL-17, IL-22, and TNF-α levels, and reduced IL-1β levels in the colon of diabetic mice compared to non-diabetic controls, without altering the content of IL-4, IL-6, and TGF- β1." (PMID 40496562, 2025). "This comparison demonstrated that diabetes may lead to an increase in the levels of IL-2 and TNF-α without altering the levels of IL-4, IL-5, and INF-ɣ (p>0.05)." (PMID 37842429, 2023). "The induction of diabetes mellitus leads to the initiation of the inflammatory process and the release of pro-inflammatory cytokines such as IL-2 and TNF-α and does not produce any change in the levels of IL-4, IL-5, and INF-ɣ." (PMID 37842429, 2023).
Arthritis (110 papers, 2005 to 2026). Inflammation of a joint. "On the other hand, IL-4 deficiency reduces the titers of pathogenic autoantibodies, slowing down the progression of arthritis." (PMID 39290695, 2024). "Treatment of mice with GRP78 intravenously or subcutaneously during the active phase of the collagen induced arthritis model reduced disease severity and led to increased IL-4, IL-5, and IL-10 (associated with dampening immune responses) production." (PMID 30978945, 2019). "Functionally, activation of the STAT6 pathway by IL-4/IL-13 plays a critical role in mitigating and resolving immune activation associated with arthritis." (PMID 27273006, 2016). "As both IFN-γ and IL-4 suppress IL-17 in vitro, one would expect that the increased severity of arthritis seen with anti-IFN-γ + anti-IL-4 would be associated with increased IL-17." (PMID 19852819, 2009). "Although similar frequency of articular lesions was observed in IL-4−/− and wt mice, IL-4 deficient group had a more severe clinical arthritis in affected joints, compared with the control animals, resulting in a higher arthritis index." (PMID 19606256, 2009). "The IFNγ: IL-4 ratio shifted toward the Th1 direction in the older, arthritis-susceptible mice, while in the arthritis-resistant 1-month-old group these two signature cytokines were produced in approximately equal amounts." (PMID 19519881, 2009). "Additionally, both IL-4 and IL-13 have been consistently associated with arthritis and implicated in the downregulation of the inflammatory process, thereby associated with reduced pain in one literature review." (PMID 40649738, 2025). "Osteoclast differentiation, bone loss and cartilage damage were significantly diminished after N. brasiliensis infection but not in the respective mutant mice, suggesting that control of arthritis by the IL-4/IL-13/STAT6 pathway is associated with substantial protection from joint damage." (PMID 27273006, 2016). "Interestingly, in an adjuvant-free arthritis model an increased IL-4 and IL-5 production was associated with eosinophil infiltration in ROS deficient mice." (PMID 24358335, 2013). "The ability of IL-4 to suppress reactivation of committed Th17 cells may be another mechanism by with IL-4 deficiency could contribute to arthritis in SJIA." (PMID 23092393, 2012). "Deficiency of IL-4 is associated with increased severity of arthritis in a mouse model." (PMID 21385363, 2011). "It is possible that the increased arthritis in the presence of anti-IFN-γ + anti IL-4 is associated with the generation of a more aggressive phenotype of Th17 cells, one that may be associated with reduced levels of IL-10." (PMID 19852819, 2009). "While IFNγ-deficient BALB/c mice developed less severe arthritis, IL-4-/- mice in the same background aggravated the response to PG immunization: an earlier onset with more severe inflammation was detected when compared to age- and gender-matched wild-type mice." (PMID 19519881, 2009). "However, it has also been suggested that IL-4 might have pathogenic effects during the early phase of arthritis." (PMID 19852819, 2009). "Administration of 26 mg/kg of the extract had maximally reduced the symptoms of arthritis, improved protective mediators (IL-4), decreased inflammatory cytokines (IL-1β, IL-6, IL-17, and IFN-γ), and restored joint structure." (PMID 41495193, 2026). "A total of 6 mg/kg/d for 22 days improved foot-plantar swelling and arthritis scores in RA rats and regulated the balance of pro-inflammatory factors, such as IL-1β, IL-6, and IL-17A, and anti-inflammatory factors, such as IL-4 and IL-10." (PMID 40864815, 2025). "The role of IL-4 treatment in slowing down disease progression has also been confirmed in animal models of experimental arthritis." (PMID 39596150, 2024).